PURPL (p53 upregulated regulator of p53 levels)
Synonyms: LOC643401; RP11-46C20.1; LINC01021
Gene: Long non-coding RNA gene on chromosome 5 (27,217,714 to 27,497,871, forward strand). Ensembl gene ENSG00000250337.
Diseases named in the same sentence as PURPL in open-access papers:
PURPL is named in the same sentence as 20 diseases in open-access papers, as found by Europe PMC text mining. Sharing a sentence is not in itself a finding about the gene and the disease. The quoted sentences say what the papers report.
colorectal cancer (18 papers, 2016 to 2025). A primary or metastatic malignant neoplasm that affects the colon or rectum. "The lncRNA PURPL was first identified as overexpressed and promotive of tumorigenesis in colorectal cancer." (PMID 37781085, 2023). "lncRNA PURPL, a proto-oncogene, exerts an essential cancer-promoting function in colorectal cancer and hepatocellular carcinoma." (PMID 35012438, 2022). "As proved in earlier studies, PURPL played a tumor-promoting role in colorectal cancer, gastric cancer, and liver cancer." (PMID 34686652, 2021). "PURPL was reported to be involved in the development and progression of colorectal cancer, liver cancer and gastric cancer 30-32." (PMID 34405027, 2021). "Since PURPL is mainly localized in cytoplasm, the role of PURPL in melanoma should be quite different from the role in colorectal cancer." (PMID 34759263, 2021). "We were intrigued whether PURPL, which was shown to be upregulated in colorectal cancer, which is highly aneuploid, had anything to do with aneuploidy." (PMID 39763585, 2024). "We were curious to investigate whether PURPL, a gene that has been found to be increased in colorectal cancer, which is characterized by a high number of abnormal chromosomes, is associated with aneuploidy." (PMID 39763585, 2024).
liver cancer (6 papers, 2021 to 2024). An epithelial or non-epithelial malignant neoplasm that arises from the liver. "The subsequent observations reported analogous expression profiles and carcinogenic effects of PURPL in liver cancer 34, gastric cancer 35, and ovarian cancer." (PMID 37781085, 2023). "To investigate loss-of-function of PURPL in liver cancer, we designed three LNA-modified gapmer ASOs targeting PURPL." (PMID 36376362, 2022). "PURPL has been reported to be upregulated in liver cancer cell lines, although its exact mechanism remains unclear." (PMID 39336111, 2024). "Additionally, knockdown of PURPL inhibited cell growth and induced apoptotic activity in liver cancer cells." (PMID 36376362, 2022). "Interestingly, a decreased level of PURPL mediated by ASOs enhances the response to the chemotherapeutic agent doxorubicin (DOX) in cultured liver cancer cells, suggesting that PURPL may have therapeutic potential in the treatment of chemoresistant HCC." (PMID 36376362, 2022). "Furthermore, knockdown of PURPL significantly decreased proliferation of HepG2 (P = 0.02, 72 h) and Sk-hep-1 cells (P = 0.006, 48 h; P = 0.02, 72 h), suggesting that PURPL could function as a potential pro-survival gene in liver cancer." (PMID 36376362, 2022).
gastric cancer (5 papers, 2021 to 2025). A primary or metastatic malignant neoplasm involving the stomach. "Our study reveals that lncRNA PURPL is an underlying target for gastric cancer treatment, also an essential indicator for projecting its prognosis." (PMID 35012438, 2022). "To grasp the expression features of PURPL in gastric cancer tissues, we gleaned the tumor tissues and normal adjacent tissues of 21 patients suffering from gastric cancer and determined PURPL expression in the tissues employing RT-PCR." (PMID 35012438, 2022). "Given the outcomes, we concluded that lncRNA PURPL presented a high profile in gastric cancer tissues and gastric cancer cells." (PMID 35012438, 2022). "FISH indicated that PURPL was primarily situated at the cytoplasm of gastric cancer cells, while its level was lessened in the adjacent normal tissues." (PMID 35012438, 2022). "PURPL expression was prominently enhanced in gastric cancer tissues as compared with normal tissues (p < 0.05)." (PMID 35012438, 2022). "To delve into the function of lncRNA PURPL in the miR-137/ZBTB7A axis in the field of gastric cancer, we transfected miR-137 mimics (miR-137) or si-ZBTB7A into the AGS cell model with overexpression of PURPL." (PMID 35012438, 2022). "Furthermore, PURPL is overexpressed in gastric cancer, where it promotes cell growth, migration, survival, and invasion." (PMID 41170526, 2025). "In this study, attempts were made to explore lncRNA PURPL’s regulation on miR-137 and ZBTB7A molecules as well as its impact on the development of gastric cancer." (PMID 35012438, 2022). "RT-PCR confirmed the profile of PURPL in the normal gastric epithelial cell line GES-1 and gastric cancer cell lines AGS, GC9811-P, MKN-45, and HSC-39." (PMID 35012438, 2022). "PURPL, also known as LINC01021, was detected to be upregulated in gastric cancer tissue, and was related to tumor size and histopathological grade, which indicated poor clinical outcomes." (PMID 34405027, 2021). "Nevertheless, the function of lncRNA PURPL in gastric cancer progression has not been elucidated so far." (PMID 35012438, 2022).
melanoma (5 papers, 2021 to 2025). A malignant, usually aggressive tumor composed of atypical, neoplastic melanocytes. "Collectively, the in vivo experiments indicated that PURPL functions in repressing autophagic cell death to promote melanoma growth by differentially modulating ULK1 phosphorylations." (PMID 34759263, 2021). "To extend this analysis to clinic samples, we collected and verified higher expression of PURPL in melanoma tumors compared with normal skins." (PMID 34759263, 2021). "As predicted, higher expression of PURPL (stronger staining) can be detected in all melanoma tumors examined." (PMID 34759263, 2021). "One of the top ten highest-expressed genes is PURPL which is ranked as the eighth highest-expressed gene and the highest-expressed LncRNA in melanoma." (PMID 34759263, 2021). "Matrigel invasiveness measurement showed that knockdown of PURPL also significantly compromised the invasive capacity of melanoma cells." (PMID 34759263, 2021). "The higher expression of PURPL was practically validated by examining the expression levels of PURPL in the melanoma cell lines (A375, SK-MEL-1 and SK-MEL-28) compared with the primary normal human epidermal melanocytes (NHEM)." (PMID 34759263, 2021). "We also checked PURPL expression in The Cancer Genome Atlas Program (TCGA) database and confirmed the higher expression levels of PURPL in melanoma group compared with normal group." (PMID 34759263, 2021). "PURPL functions as an oncogene by promoting the proliferation, colony formation, migration, and invasiveness of melanoma cells." (PMID 34759263, 2021). "Conversely, overexpression of PURPL in A375 cells promoted melanoma cell proliferation, colony formation, migration, and invasiveness compared with cells transfected with empty vector." (PMID 34759263, 2021). "PURPL physically interacts with ULK1 and differentially regulates its phosphorylation by promoting the association with mTOR and departure from AMPK to suppress autophagic cell death for maintaining the survivability of melanoma cells." (PMID 36918934, 2023). "Our findings highlight a novel oncogenic role of PURPL to suppress autophagic cell death mediated by regulating differential ULK1 phosphorylation in melanoma, which may provide novel intervention targets for melanoma therapy." (PMID 34759263, 2021). "Seeing the current theory that LncRNAs play roles by associating with proteins, RNA pulldown assay was performed using an in vitro-transcribed full-length PURPL RNA together with a control EGFP RNA to explore how PURPL knockdown inhibits the proliferation of melanoma." (PMID 34759263, 2021). "Importantly, PURPL expression was further examined in paraffin-embedded sections of 52 melanoma and 10 normal skin specimens by in situ hybridization (ISH)." (PMID 34759263, 2021). "Our findings highlight the oncogenic and autophagy-suppressive roles of PURPL in melanoma and emphasize a novel mechanism to repress autophagic cell death, which may provide novel intervention targets for melanoma therapy." (PMID 34759263, 2021). "Collectively, our study showed PURPL is highly expressed in melanoma and its subcellular localization is mainly in cytoplasm, which is drastically different compared from previous report and drives us to explore the role of PURPL in cytoplasm." (PMID 34759263, 2021). "Further scoring of PURPL staining showed a positive correlation with ascending melanoma grade." (PMID 34759263, 2021).
melanoma (continued). "To validate if PURPL regulates autophagy, we treated melanoma cells with autophagy inhibitor 3-MA." (PMID 34759263, 2021). "The upregulation of PURPL in melanoma prompted that PURPL may have an oncogenic role in melanoma development." (PMID 34759263, 2021). "Thus, we hypothesized that PURPL intervenes in autophagy to modulate melanoma progression by directly interacting with ULK1 and mTOR." (PMID 34759263, 2021). "Depletion of PURPL leads to AMPK-mediated phosphorylation of ULK1 at Ser555 and Ser317, which promotes autophagic cell death and thereby inhibits melanoma development." (PMID 40651979, 2025). "Previously, we have shown LncRNA PURPL directly interacts with ULK1 to promote mTOR-mediated phosphorylation of ULK1 at Ser757 to repress autophagic cell death and promote melanoma cell survival." (PMID 40651979, 2025). "Depletion of PURPL significantly increased the amount of LC3B-II, reduced the p62 expression and promoted the formation of LC3B foci in melanoma cells, which indicates the enhancement of autophagic flux." (PMID 34759263, 2021). "Mechanistic study showed that PURPL physically interacts with ULK1 and differentially regulates its phosphorylation to suppress autophagic cell death to maintain the survivability of melanoma cells." (PMID 34759263, 2021). "Before we start the mechanistic study, the subcellular localization of PURPL in melanoma cells was detected with fluorescent in situ hybridization (FISH) and observed distinct cytoplasmic localization of PURPL, while small portion of PURPL is indeed in nucleus." (PMID 34759263, 2021). "Our results identify PURPL as a key regulator to modulate the activity of autophagy initiation factor ULK1 to repress autophagic cell death in melanoma and may represent a potential intervention target for melanoma therapy." (PMID 34759263, 2021).
hepatocellular carcinoma (3 papers, 2022 to 2024). A malignant tumor that arises from hepatocytes. "We confirmed increased expression of PURPL in HCC using data from The Cancer Genome Atlas (TCGA) and Genetype-Tissue Expression (GTEx) database (P = 4.10E-8, TCGA-Liver Hepatocellular Carcinoma (LIHC): n = 369, Normal liver tissue: n = 160)." (PMID 36376362, 2022).
ovarian carcinoma (3 papers, 2021 to 2023). A malignant neoplasm originating from the surface ovarian epithelium. "This implies that PURPL could be implicated in the initiation and progression of ovarian cancer, and could serve as a prognostic indicator for adverse outcomes in ovarian cancer." (PMID 37781085, 2023). "Our previous research ascertained that PURPL is upregulated in ovarian cancer, and its upregulation correlates with poor Recurrence-Free Survival (RFS) and OS for ovarian cancer patients." (PMID 37781085, 2023). "Then, real time PCR was performed to confirm the expressions of PURPL in different collected ovarian tissues, and to explore the significance of PURPL and miR-338-3p in the prognosis of ovarian cancer." (PMID 34405027, 2021). "Compared to paired normal ovarian samples, upregulated profiles of PURPL were detected in ovarian carcinoma tissues among human malignant tumors." (PMID 34405027, 2021). "Upregulation of PURPL was related with the recurrence (P=0.002, OR=21.482, 95%CI: 3.457~94.251) and death (P=0.004, OR=35.643, 95%CI: 2.453~84.359) of ovarian cancer patient." (PMID 34405027, 2021). "Kaplan-Meier analysis was implemented to evaluate the relations between PURPL and miR-338-3p expressions and the survival of ovarian cancer." (PMID 34405027, 2021). "To verify the results queried in biomedical databases, we also collected normal, benign and malignant ovarian tissues to analyze the roles of PURPL in the ovarian cancer." (PMID 34405027, 2021). "In the present study, we tried to query the expression of PURPL and its relation with the prognosis of ovarian cancer in biomedical databases." (PMID 34405027, 2021). "To verify the biomedical database query results, we collected normal ovarian, benign ovarian epithelial tumor and epithelial ovarian cancer tissues to analyze the expression profile of PURPL." (PMID 34405027, 2021). "Higher expressions of PURPL were associated with more advanced FIGO stage and developed lymph node metastasis in epithelial ovarian cancer." (PMID 34405027, 2021). "PURPL was upregulated in several human cancers, including ovarian cancer." (PMID 34405027, 2021). "However, relative expression level of PURPL in 65 cases ovarian cancer tissues was (0.522±0.004), which indicated an obviously upregulated expression profile of PURPL in ovarian cancer tissues (F=6676.000, P<0.0001)." (PMID 34405027, 2021). "Our data showed upregulations of PURPL were noted in ovarian cancer tissues." (PMID 34405027, 2021). "The median relative level of PURPL in 65 cases of epithelial ovarian cancer was (0.525±0.006), which was used to divide PURPL expression into relatively high group (higher than or equal to the median expression) and relatively low group (lower than the median expression)." (PMID 34405027, 2021). "Rare reports were involved in the relations between PURPL and ovarian cancer." (PMID 34405027, 2021). "Instead of normal ovarian tissues and benign ovarian tumor tissues, obvious upregulations of PURPL were measured in EOC tissues, which suggested abnormal expression of PURPL might be implicated in the carcinogenesis of ovarian cancer." (PMID 34405027, 2021). "Upregulation of PURPL indicated poor RFS and OS for ovarian cancer patients." (PMID 34405027, 2021). "Based on three TCGA databases including 1680 samples from 1668 ovarian cancer patients, we noted a negative expression profile between PURPL and miR-338-3p in ovarian cancer tissues." (PMID 34405027, 2021).
ovarian carcinoma (continued). "The roles of PURPL involved in ovarian cancer have never been reported." (PMID 34405027, 2021). "Compared to patients with low expression of PURPL, patients with high expression of PURPL showed shorter recurrence free survival (RFS) time and overall survival (OS) time, which was queried in Kaplan-Meier Plotter Pan-Cancer database including 374 ovarian cancer patients." (PMID 34405027, 2021).